EFNA1 (ephrin A1)
Diseases named in the same sentence as EFNA1 in open-access papers (continued):
Sharing a sentence is not in itself a finding about the gene and the disease.
tumor (continued). "Over-expression of ephrin-A1 in tumor cells can promote the angiogenic process, while knock down of ephrin-A1 in tumor cells contributes significantly to reduction of tumor-induced endothelial cell migration in vitro and microvascular density in vivo." (PMID 24040255, 2013). "Ephrin-A1 and its primary receptor, EphA2, are not only expressed in multiple malignancies, but also play a vital role in normal angiogenesis and tumor neovascularization." (PMID 24040255, 2013). "Our data confirmed that both ephrin-A1 expression and soluble ephrin-A1 secretion in tumor cells were increased under hypoxia stimulation." (PMID 24040255, 2013). "Overall, these results suggest that ephrin-A1 plays an important role in tumor progression, but the exact function is complex, cell-type dependent and most likely relies on many factors, including its preferred receptor EphA2." (PMID 22853000, 2012). "Ephrin-A1 is supposed to act as a tumor suppressor through its preferred receptor EphA2 which is overexpressed in NSCLC." (PMID 22853000, 2012). "We report a novel mechanism of ephrin-A1 mediated attenuation of NSCLC tumor growth due to down regulation of claudin-2 and induction of tumor suppressor gene cdx-2." (PMID 22824143, 2012). "The staining intensity of S100A4 and ephrin-A1 was generally homogenous across the sections, indicating that the obtained results are indeed representative of the whole tumor section." (PMID 22853000, 2012). "Recent studies demonstrate the additional involvement of ephrin-A1 and EphA2 in postnatal and tumor angiogenesis." (PMID 22363788, 2012). "We demonstrate that activation of receptor EphA2 with ephrin-A1 induced cdx-2 expression and inhibited tumor formation." (PMID 22824143, 2012). "Receptor EphA2 and its ligand ephrin-A1 form an important cell communication system with its functional role in cell-cell interaction and tumor growth." (PMID 22824143, 2012). "Whereas, the forced expression of ephrin-A1 induced tumor suppressive signals via downregulation and degradation EphA2 and inhibited the oncogenic singling pathway in NSCLC." (PMID 22824143, 2012). "Ephrin-A1 is involved in multiple biological processes, including tumor angiogenesis, cell motility and metastasis." (PMID 22853000, 2012). "Ephrin-A1 activation or transfection of cells with plasmid containing the ephrin-A1 construct inhibits the expression of claudin-2 confirming its anti-tumor effects on NSCLC cells." (PMID 22824143, 2012). "We found that forced expression of ephrin-A1 down regulated the receptor EphA2 and inhibited cell proliferation and tumor growth in 3D matrigel." (PMID 22824143, 2012). "In contrast, LCN2 was exclusively downregulated in SC, while EFNA1 expression decreased with tumor dedifferentiation." (PMID 21333016, 2011). "Our study identifies a tumor-specific SE at the EFNA1 locus that drives EFNA1 expression in CC." (PMID 39964764, 2025). "This specificity may be attributed to the selective recruitment of key TFs, such as FOSL2, to the SE regions in these tumor types, highlighting a potential mechanism for EFNA1-SE–driven oncogenesis in CC and beyond." (PMID 39964764, 2025). "Moreover, IHC staining in an expanded CC patient cohort (n = 109) demonstrated a positive correlation between EFNA1 expression and tumor staging." (PMID 39964764, 2025). "EFNA1 drives tumor progression through Src/AKT/STAT3 pathway activation." (PMID 39964764, 2025). "Among the numerous EFNA1 variants, the rs12904 (A>G) variant situated within the 3′ UTR has been the focus of extensive investigation due to its influence on EFNA1 expression and tumor angiogenesis." (PMID 40004552, 2025). "Although EphA2 signaling is generally associated with tumor-suppressive effects, its activation in this context may paradoxically promote angiogenesis via VEGF-A and TNF, likely influenced by high ephrin-A1 expression in endothelial cells." (PMID 41200151, 2025).
tumor (continued). "Moreover, functional assays confirmed that SCNN1A and EFNA1 are highly expressed in well-differentiated tumor cell subpopulations and contribute to tumor progression by modulating cell migration, invasion, and immune evasion." (PMID 40787466, 2025). "EFNA1 knockdown strikingly reduced CC cell proliferation, migration, and tumor growth." (PMID 39964764, 2025). "Therefore, it is worthwhile to further investigate the function of Ephrin A1-EGFR axis in other tumor types." (PMID 39838173, 2025). "Additionally, an in vivo xenograft model revealed that EFNA1 overexpression markedly promoted tumor growth in CC cells." (PMID 39964764, 2025). "EPHA2 has been demonstrated to regulate multiple cellular processes in embryonic development, angiogenesis, and tumor occurrence through EphA2-ephrin A1 signaling transduction, including proliferation, survival, migration, morphology, cell repulsion, and adhesion." (PMID 38773226, 2024). "In mesothelioma, EFNA1 could suppress the tumor growth via the induction of miR-320b-regulated apoptosis and the miRNA let-7-mediated repression of the RAS expression." (PMID 37160815, 2023). "The differential gene expression levels between the tumor and adjacent tissue indicated that the ROBO1, KLK6, LIMK2, KLK7, NLGN4X, MBP, and NEDD9 gene expression levels were higher in normal tissues than in tumors; however, EFNA1 was higher in the tumor than the normal ones." (PMID 38137332, 2023). "Furthermore, we constructed xenograft tumors in mice to evaluate the effects of EFNA1 on tumor growth in vivo." (PMID 37160815, 2023). "Likewise, cellular pretreatment of the tumor cells with MEDI3622 abrogated the release of ephrin-A1 into the supernatant." (PMID 36998455, 2023). "EFNA1 suppresses tumor growth whereas PGE2 supports tumor growth by promoting angiogenesis." (PMID 38036781, 2023). "In addition, the expression levels of EFNA1 (P = 2.68E−02), TNFAIP8 (P = 2.77E−02), and TNFAIP8L3 (P = 6.48E−03) showed a significant association with tumour stage." (PMID 34344926, 2021). "Soluble forms of ephrin-A1 in serum were increased in tumor-bearing mice." (PMID 33804570, 2021). "Moreover, we also reported that the soluble form of ephrin-A1 was increased in the serum of tumor-bearing mice." (PMID 33804570, 2021). "While much of the published literature on ephrin-A1 focuses on its tumor suppressive role in the tumor cell, this novel study demonstrates that its role in the host tissues may be tumor-promoting." (PMID 32399207, 2020). "In summary, host deficiency in ephrin-A1 does not significantly affect tumor-infiltrating immune cells in both primary tumors and tumor-bearing lungs." (PMID 32399207, 2020). "Together, our studies suggest that host deficiency of ephrin-A1 does not impact initial tumor growth but does affect metastasis through inhibiting cancer cell extravasation and proliferation at the metastatic niche." (PMID 32399207, 2020). "Additionally, ephrin-A1 on these cell types presumably interacts with EphA receptors on various stromal and tumor cells." (PMID 32399207, 2020). "EFNA1 could also interact with ephrin receptor EPHA1, which is overexpressed in PTC and then associates with tumor growth, invasiveness, and metastasis, to trigger transcription factor PDX1, which is modified by phosphorylation to cause its activation." (PMID 31126066, 2019). "Indeed, a changing trend of MVD similar to that of ephrin-A1 expression in tumor tissue was also observed (p < 0.05)." (PMID 29367676, 2018). "Eph receptor A1 and ephrin A1 complexes maintain cell-cell adhesion between endothelial cells, however enhancing ADAM12-mediated shedding of ephrin A1 by TGF-β1 in primary tumors results in lung hyperpermeability that allows tumor cells to extravasate into the lungs." (PMID 28260841, 2017).
tumor (continued). "In fact, the first Eph receptor (EphA1) and the first ephrine (ephrin-A1) were both identified as tumor antigens from carcinoma cell lines, and their overexpression could lead to oncogenic transformation in NIH3T3 fibroblasts." (PMID 26989075, 2016). "Our results suggested that up-regulated ephrin-A1 in tumor hypoxic microenvironment may promote angiogenesis via PI3K/Akt/eNOS pathway." (PMID 24040255, 2013). "In our previously published report we showed that S100A4, OPN and ephrin-A1 were highly expressed in NSCLC tumor tissue, and that S100A4 expression was associated with adenocarcinoma histology, as well as with small tumor size and high degree of differentiation." (PMID 24215488, 2013). "Hypoxia could actively induce enhancement of both membrane-bound and soluble ephrin-A1 in tumor cells." (PMID 24040255, 2013). "Although morphological changes of U-251 cells were observed under CM stimulation, further functional experiments are still necessary to demonstrate whether hypoxia-induced soluble ephrin-A1 can induce EphA2 phosphorylation or even tumor angiogenesis." (PMID 24040255, 2013). "However, EphA2 can also act as a tumor suppressor, and recently, high expression of both EphA2 and ephrin-A1 was found to be related to favorable prognostic factors in stage I NSCLC patients." (PMID 22853000, 2012). "Activation of NSCLC cells with ephrin-A1 leads to tumor growth inhibition via cdx-2 expression." (PMID 22824143, 2012). "Furthermore, silencing cdx-2 gene expression before ephrin-A1 treatment increased claudin-2 expression along with increased cell proliferation and tumor growth in A549 cells." (PMID 22824143, 2012). "We conclude that receptor EphA2 activation by ephrin-A1 induces tumor suppressor gene cdx-2 expression which attenuates cell proliferation, tumor growth and thus may be a promising therapeutic target against NSCLC." (PMID 22824143, 2012). "Immunohistochemical staining for S100A4, ephrin-A1 and osteopontin was performed on tissue microarrays containing primary tumor samples from a cohort of 217 prospectively recruited NSCLC patients, and associations with clinicopathological parameters were investigated." (PMID 22853000, 2012). "The molecular mechanisms responsible for tumor suppressive effects of ephrin-A1 are still elusive." (PMID 22824143, 2012). "We stained duplicate slides with anti-ephrin-A1 or anti-EphA2 antibodies that were validated using mammary tissue from genetic deletion mouse models and quantified the percent positive tumor epithelium and relative staining intensity using a computer-based Ariol platform." (PMID 21935409, 2011). "Also, the canonical intracellular signaling induced by EphA2 after binding to its natural ligand (Ephrin A1) plays a tumor-suppressive role in epithelial cells by inducing a cascade of reactions beyond the EphA2 (this is called the “forward effect” of EphA2/Ephrin A1 interaction)." (PMID 40943407, 2025). "Since most of the tumor markers identified so far are not specific to a particular tumor type, we can speculate that EFNA1 combined with MMP13 may also have potential diagnostic value for other tumor types, which needs future evaluation." (PMID 38987376, 2024). "Moreover, EFNA1 combined with MMP13 potentially demonstrated a better diagnostic sensitivity for early-stage GC patients than markers CEA and CA19-9, which are major serum tumor markers in gastrointestinal cancers currently used in clinical practice." (PMID 38987376, 2024). "However, there are researches indicating otherwise of EFNA1 affecting tumor progression." (PMID 37160815, 2023). "To explore the roles of EFNA1 on tumor progression, we constructed EFNA1 knockdown cells by transfecting lentivirus containing two independent shRNA targeted to EFNA1. qRT-PCR and western blot analysis showed each shRNA could cause remarkably decreased expression of EFNA1." (PMID 37160815, 2023).
tumor (continued). "Notably, while EFNA1 depletion clearly reduced tumor-suppressive EphA2-pY588, as expected upon depletion of the ligand-mediated signaling, EFNA5 silencing left EphA2-pY588 essentially unaltered in OVCAR3 and even increased this tyrosine phosphorylated receptor in OVCAR4." (PMID 33893375, 2021). "Tumor invasion is associated with ESCA staging; patients with ESCA with lesions confined to the mucosa have a better prognosis, suggesting that tumors with highly expressed EFNA1 may have a higher malignant biological potential." (PMID 34399788, 2021). "Together, these results demonstrate that while host deficiency in ephrin-A1 may not affect initial tumor growth, it can impact metastatic spread and recurrence.Underlying data are available." (PMID 32399207, 2020). "The tumor suppressors genes such as EFNA1 (Ephrin-A1), ERRFI1 (ERBB Receptor Feedback Inhibitor 1), LATS2 (Large Tumor Suppressor Kinase 2) and PLK2 (Polo-Like Kinase 2) also show higher average expression in PD0325901 resistant cell lines and thus may be contributing to PD0325901 resistance." (PMID 27030518, 2016). "Interestingly, Efna1 plays a role in tumor growth regulation." (PMID 24652767, 2014). "Therefore, our results suggested that up-regulation of membrane-bound ephrin-A1 induced by hypoxia may promote tumor angiogenesis through interaction with its receptor EphA2 on endothelial cells in tumor microenvironment." (PMID 24040255, 2013). "Silencing the expression of EphA2 receptor also increases the expression of cdx-2 which indicates that knockdown of EphA2 either by ephrin-A1 activation or by silencing interference RNA could be potential in inhibiting the oncogenic effect of receptor EphA2 and tumor growth." (PMID 22824143, 2012). "In addition, when the A549 cells were transfected with cdx-2 siRNA and subsequently treated with the ephrin-A1 or transfected with pcDNA-EFNA1 we noticed significantly increased tumor formation as compared to cells either activated with ephrin-A1 alone and pcDNA-EFNA1 transfected cells." (PMID 22824143, 2012). "In addition, ephrin-A1-Fc was found to inhibit tumor growth and migration in NSCLC cells." (PMID 22853000, 2012). "In the RM+ group under 2D conditions, tumour suppressor genes, CDKN1A and NR4A3, were upregulated and tumour-promoting genes, CA9, EFNA1, and SUSD2, were downregulated." (PMID 41381717, 2025). "The miR-200 family, particularly miR-200c and miR-200a-3p, has been demonstrated to regulate the ephrin genes EFNA1 and EFNA5, thereby influencing tumor growth and metastasis." (PMID 40004552, 2025). "RNA sequencing revealed upregulation of tumour suppressor genes, including CDKN1A and NR4A331,32, and downregulation of tumour-promoting genes, including CA9, EFNA1, and SUSD233–36." (PMID 41381717, 2025). "Our study further elucidates a functional mechanism where EFNA1 cis-interacts with its receptor EphA2, leading to EphA2 degradation and subsequent activation of the Src/AKT/STAT3 pathway, thereby promoting tumor progression in CC." (PMID 39964764, 2025). "A large number of studies have shown that EFNA1 is often overexpressed in human gastrointestinal tumors such as CRC, EC and HCC, and the degree of up-regulation of EFNA1 is closely related to tumor malignancy, metastasis potential and patient prognosis." (PMID 38987376, 2024). "The level of soluble ephrin-A1 was strongly reduced in NCI-H358 and PC-3 tumor cells treated with the ADAM17 inhibitor." (PMID 36998455, 2023). "Salvianolic acid A (SAA), screened as a small molecular medicine targeting EFNA1 via molecular docking, showed significant inhibitory effects on ESCC cell proliferation and tumor growth." (PMID 37160815, 2023). "Small molecules aiming at the G-H loop of EFNA1 and the ligand binding domain of EPHA2, such as lithocholic acid and the SWL peptide, have also been screened but remained to be tested for tumor treatment." (PMID 37160815, 2023).
tumor (continued). "However, anti-angiogenic drugs may promote tumor progression and distant metastasis, which may be related to tumor hypoxia and the expression of vascular endothelial growth factor A, fibroblast growth factor, ephrin A1, and the activation of the proto-oncogene c-Met." (PMID 36248960, 2022). "The expression of EFNA1, EFNA3, EFNA4, EFNB1, and EFNB2 was significantly increased in tumor tissues compared with normal tissues." (PMID 36052169, 2022). "We found that the expression of EFNA1, EFNA2, EFNA3, EFNA4, EFNB1, and EFNB2 was upregulated in the tumor tissues of most cancers compared with corresponding normal tissues." (PMID 36052169, 2022). "In HCC, the expression levels of EFNA1, EFNA3, EFNA4, EFNB1, and EFNB2 were significantly higher in tumor tissues than in normal tissues." (PMID 36052169, 2022). "The results indicated that the expression of tumor cell-derived VEGFA, IGFBP3, EFNA1, EFNB1, IGF2, PDGFA and stroma-derived Angpt2, Cdh5, Esam, Esm1, Icam2, and Tie1 was statistically correlated with that of Pecam1 and elevated in p-EMT TW2.6 tumors." (PMID 34869001, 2021). "EFNA1 conferred resistance to photofrin-mediated photodynamic therapy resistance in ESCC cells, and EPHA2, which was hyperphosphorylated in ESCC, promoted tumour cell proliferation, migration, invasion and epithelial–mesenchymal transition." (PMID 32732965, 2020). "Ephrin-A1 expression and MVD in tumor xenograft tissues were evaluated by immunohistochemical analysis." (PMID 29367676, 2018). "The tumor progression of the wild-type and empty vector-transfected TCCSUP cell groups was similar to each other but in contrast with that in the ephrin-A1-overexpressing TCCSUP group at the end of the experiment." (PMID 29367676, 2018). "The analysis of EPH-A2 and Ephrin-A1 transcript levels, performed in 14 ERMS primary tumours by using Real Time PCR, showed that both transcripts were significantly upregulated in all tumour samples in comparison to NSM." (PMID 28985758, 2017). "Given our in vitro results, we analyzed as to what extent Ephrin B3, Ephrin A1 and EphA2 were expressed in early stage IA-IB NSCLC tumor specimens." (PMID 27533087, 2016). "The aim of this study was to investigate S100A4-mediated stimulation of ephrin-A1 and osteopontin in non-small cell lung cancer (NSCLC) cell lines, and to characterize the expression of these biomarkers in primary tumor tissue from NSCLC patients." (PMID 22853000, 2012). "Next, we wanted to examine the expression of S100A4, ephrin-A1 and osteopontin in NSCLC tumor tissue." (PMID 22853000, 2012). "Defining the role of EphA2 and ephrin-A1 in NSCLC is particularly important, as EphA2 receptor is highly expressed in NSCLC which contributes to tumor development." (PMID 22824143, 2012). "Microscopic examination revealed that A549 cells activated with ephrin-A1 and those transfected with pcDNA-EFNA1 showed suppressed tumor growth in matrigel as compared to empty vector transfected or control cells." (PMID 22824143, 2012). "Increased tumour cell staining of EPHA2 and Ephrin-A1 was found in 23 and 72%, respectively, in ID1 strong cases, compared with 9 and 47% in ID1 weak cases." (PMID 16189525, 2005). "IHC analysis demonstrated a progressive increase in SCNN1A and EFNA1 expression from adjacent non-tumor tissue to primary tumors and metastatic foci, with notably higher levels in subpopulations of tumor cells exhibiting a higher differentiation capacity." (PMID 40787466, 2025). "We observed significantly higher EFNA1 expression in tumor regions compared with their paired non-cancerous normal tissues." (PMID 39964764, 2025). "Subsequent transcriptomic analysis of CC tissues (n = 9) and their paired adjacent non-tumor tissues revealed a substantial upregulation of key genes involved in the Src/AKT/STAT3 pathway, along with elevated EFNA1 expression in tumor samples compared with normal tissues." (PMID 39964764, 2025).